SERPINA3 (serpin family A member 3)
Diseases named in the same sentence as SERPINA3 in open-access papers (continued):
Sharing a sentence is not in itself a finding about the gene and the disease.
tumor (continued). "Through qRT-PCR on clinical samples, expression of NRP1, IGF2R, SERPINA3 and TNF were significantly upregulated in tumor tissue, while ICOS and DES were significantly downregulated." (PMID 36406134, 2022). "According to previous studies, SERPINA3 and pigment epithelium-derived factor (PEDF), members of serine protease inhibitor family, are involved in a variety of tumor progression." (PMID 34861864, 2021). "The supportive role of the tumor micro-environment is represented by proteins involved in avoiding immune destruction and inducing tumor-promoting inflammation (CRP, C9, SERPINA3)." (PMID 25114662, 2014). "While showing signs of tumor adaptation, the margin retained normal tissue characteristics, with downregulation of genes involved in iron accumulation, detoxification, and immune response (FTL, SERPINA3, IGHA1)." (PMID 40431665, 2025). "Our research group further revealed that when osteoblast-derived EVs are internalized by PCa cells, they induce the expression of SERPINA3 and LCN2, exerting tumor-suppressive effects while simultaneously promoting osteoblastic metastasis, supported by in vitro and in vivo models." (PMID 41465584, 2025). "Our research group reported that Serpin family A member 3 (SERPINA3) and Lipocalin2 (LCN2), which are upregulated in PCa and modulated by osteoblast-derived EVs, regulate PCa cell proliferation and invasion in a tumor-suppressive manner, supported by in vitro and in vivo models." (PMID 41465584, 2025). "An ATF3-transgenic mouse model that had enhanced tumor growth was also shown to have increased levels of expression of SerpinA3 in cardiac tissues but not in tumor cells." (PMID 38279150, 2024). "We noted that the expression of SERPINA3 and IGF1R/integrinα5β1 co-localized at areas of greater stromal interface, highlighting the potential interaction between the stroma and tumor cells via the SERPINA3 and IGF1R/integrinα5β1 axis." (PMID 38866016, 2024). "The genes with a significant correlation between the level of expression and the spatial proximity between tumor and stromal spots that are enriched in leptomeningeal tissues (patterns observed in multiple samples) include MT3, SERPINA3, and glial fibrillary acidic protein (GFAP)." (PMID 38866016, 2024). "Since we learned from previous literature that BUD13 could exert its function in tumor through regulating mRNA stability, we wanted to explore whether BUD13 could regulate the mRNA stability of SERPINA3." (PMID 34861864, 2021). "The three-marker panel of CLIC1, MAPRE1 and SERPINA3 exhibited significance regardless of tumor stage, grade, size, and menopausal status." (PMID 30963111, 2019). "Unfortunately, the level of SerpinA3 in plasma and tumor tissues were not reported in that study." (PMID 38279150, 2024). "Overall, these results suggested that SERPINA3 and LCN2 might act as tumor suppressors in PCa." (PMID 37408474, 2023). "Additionally, SERPINA3 and LCN2 suppress BPCa cell proliferation in an autocrine manner, suggesting that they may act as tumor suppressors in bone metastatic PCa." (PMID 37408474, 2023). "Moreover, the anti-tumor impact of silenced HOXA-AS2 was restored by miR-2116-3p inhibitor, but its tumor-promotional effect could be reversed by silenced SERPINA3." (PMID 35387643, 2022). "Three genes consisting of CLIC1, MAPRE1, and SERPINA3 in the refined TGFβ signature significantly stratified overall survival (log-rank p = 0.0141) in a larger validation cohort irrespective of menopausal status, tumor stage, grade, and size." (PMID 30963111, 2019). "Nonetheless, the changes in plasma SERPINA3 observed in our population might at least be partially explained by CTRCD and are likely not solely based on changes in expression in tumour tissue." (PMID 40087712, 2025).
cancer (61 papers, 2009 to 2026). A tumor composed of atypical neoplastic, often pleomorphic cells that invade other tissues. "Identifying the driving force behind SERPINA3 dynamics in this population is complex, as SERPINA3 is also linked to cancer and has known proliferative properties." (PMID 40087712, 2025). "SERPINA3 is an inhibitor of serine proteases that was previously found to be upregulated in various types of cancer and its elevation was associated with a worse prognosis." (PMID 41247789, 2025). "SERPINA3 has been linked to inflammatory processes in various cancer types, and has also been observed to be upregulated in cardiovascular diseases such as atherosclerosis." (PMID 41152331, 2025). "Data from the literature suggest that levels of serpinA3 predict long-term mortality in patients with HF and are also associated with several cancer types, including colorectal, gastric, breast, liver and prostate cancer." (PMID 36830690, 2023). "Altered expression of SERPINA3 in plasma, organs, cerebrospinal fluid, and urine is reportedly associated with various inflammatory diseases and cancers." (PMID 37006491, 2023). "The SERPINA3 protein plays a vital role in tumorigenesis, and its increased level is associated with worse prognosis in some cancers; therefore, it has thus far been used as a diagnostic factor in colon, breast, lung, and gastric cancers." (PMID 36672665, 2023). "Several patient, cancer and treatment characteristics were associated with SERPINA3 values." (PMID 40087712, 2025). "SERPINA3 values are linked to several patient, cancer and treatment related characteristics and a clear association between SERPINA3 values and inflammatory markers is present, justifying further investigation of its role as a diagnostic and prognostic biomarker in CTRCD." (PMID 40087712, 2025). "SerpinA3 has been implicated in cancer proliferation and invasiveness." (PMID 38279150, 2024). "Moreover, recent preclinical data identified novel pathways and mediators including the protein SerpinA3 as potential drivers of cancer progression in HF patients, suggesting HF as an individual risk factor for cancer development." (PMID 39340596, 2024). "The involvement of SERPINA3 has been implicated in various types of cancer." (PMID 38087342, 2023). "It is revealed that the up-regulation of SERPINA3 is positively associated with malignant tumors." (PMID 36500247, 2022). "An increasing body of evidence has suggested that SERPINA3 over-expression is correlated with cancer progression and dismal prognosis." (PMID 41550507, 2026). "We aimed to assess the longitudinal dynamics of circulating SERPINA3 levels in patients with cancer treated with anthracycline chemotherapy (AnC) and its relation to CTRCD." (PMID 40087712, 2025). "While previous cancer research has focused on SERPINA3 as an oncogenic factor, our research revealed the heterogeneity of SERPINA3 in cancer." (PMID 40367014, 2025). "Previously, higher SERPINA3 values were observed in a population of cancer survivors with moderate or severe CTRCD." (PMID 40087712, 2025). "In a population of cancer survivors with cancer therapy-related cardiac dysfunction (CTRCD) circulating SERPINA3 was elevated compared to age-matched controls." (PMID 40087712, 2025). "Circulating SERPINA3 levels show dynamic changes in a population of patients with cancer, with an overall decrease following AnC." (PMID 40087712, 2025). "The present study focuses on assessing the dynamics of circulating SERPINA3 in a population of patients with cancer treated with AnC." (PMID 40087712, 2025). "Baseline SERPINA3 values were significantly higher in this cancer population (p < 0.001) than in our previously reported control cohort." (PMID 40087712, 2025). "For mortality attributed to cancer, 28 proteins were statistically significant, with SERPINA3 showing the largest effect (2.79), alongside DDR1, LRG1, and GDF15 as the top contributors." (PMID 41270070, 2025).
cancer (continued). "In the current work we aimed to prospectively investigate the dynamics of circulating SERPINA3 in a cancer population treated with AnC and its relation with CTRCD." (PMID 40087712, 2025). "A role of SERPINA3 as a prognostic and predictive biomarker for cancer has been previously proposed (reviewed here:)." (PMID 40087712, 2025). "In the overall study population, a decrease in SERPINA3 is apparent within 3 months after the end of AnC, possibly reflecting normalisation of levels due to cancer treatment." (PMID 40087712, 2025). "Previously, we showed that SERPINA3(N) correlated with cancer treatment-induced reduction of LVEF in both humans and mice." (PMID 39367508, 2024). "Differently, numerous research revealed that SERPINA3 functioned as a promoter in cancer progression." (PMID 38440732, 2024). "The authors selected five proteins considered to be involved in the pathophysiological overlap between HF and cancer, of which SerpinA3, also known as α-1-antichymotrypsin, was increased in patients with HF and promoted cell proliferation in colon tumours." (PMID 36830690, 2023). "In cancer cells, the nuclear fraction of the SERPINA3 protein can activate the MAPK/ERK 1/2 and PI3κδ pathways by stimulating the NF-κβ signaling pathway and AKT phosphorylation and stopping the transition from the G2 phase to the M phase." (PMID 36672665, 2023). "It has been observed that silencing the expression of the SERPINA3 gene leads to the inhibition of proliferation of cancer cells by stopping the cell cycle in the G2/M phase, which consequently leads to apoptosis." (PMID 36672665, 2023). "SERPINA3 is mainly involved in processes related to cell survival and proliferation, and plays a key role in various types of cancer." (PMID 35454784, 2022). "Serine proteinase inhibitor A3 (SERPINA3), also known as alpha-1 antichymotrypsin, has been shown to promote the development of cancer and cardiac remodeling in patients with HF." (PMID 36712235, 2022). "Recent studies have shown that SERPINA3 acts as a key molecule for survival prediction in various cancers." (PMID 34449972, 2021). "Analysis of the GEO database indicated that cancer samples with SERPINA3 transcripts (n = 104) had a significantly higher expression than normal samples (n = 17) (P < 0.0001) and this was also shown in data from the TCGA." (PMID 33569740, 2021). "Recently, up-regulated SERPINA3 expression has been reported in multiple cancer types, including cancers of the colon, breast, prostate, and stomach." (PMID 27213583, 2017). "Other candidates included DDC, MANEA, ZWINT, while ERG and SERPINA3 were examples of genes scored with decreased expression in LNCaP compared to CD26+ cancer." (PMID 20021671, 2009). "In a cancer population, circulating SERPINA3 levels show a dynamic response following AnC." (PMID 40087712, 2025). "Research has highlighted the involvement of SERPINA3 in various cancers." (PMID 40565234, 2025). "Finally, assessment of normal values of circulating SERPINA3 and its variation in healthy controls and cancer patients are needed to provide clinically useful cut-off values." (PMID 40087712, 2025). "Additionally, SERPINA3 has known proliferative properties which is important in the setting of a cancer diagnosis." (PMID 40087712, 2025). "Interestingly, SERPINA3 acts on both cancer cells and immune cells by inhibiting the immune response to tumors." (PMID 36672665, 2023). "Further elucidation of SERPINA3-mediated cancer development and its involved pathway might shed light on the realm of cancer therapeutics." (PMID 37414914, 2023). "RBP4 and SERPINA3 were expressed in both the cancer cell cytoplasm and the immune cell cytoplasm." (PMID 37313408, 2023). "C9 and SERPINA3 are elevated in blood of patients with various types of cancers." (PMID 29513714, 2018). "However, SERPINA3 values differed over time according to sex, cancer type and treatment modalities." (PMID 40087712, 2025).
cancer (continued). "However, the mechanism of action and the effectors of SERPINA3 in cancer remain obscure." (PMID 38087342, 2023). "Thus, it is reasonable to assume that SERPINA3 may play an essential role in the immune process of cancer." (PMID 34449972, 2021). "Attention should be given to standardization of cancer subtype and treatment (DOX dose equivalent, concomitant treatment) to decrease the influence of cofounding factors on the relationship between SERPINA3 values and CTRCD." (PMID 40087712, 2025). "In fact, both SERPINA3 and LCN2 were reported as both oncogenes and tumor suppressors in cancer, and their roles are likely to be tissue specific." (PMID 37408474, 2023). "SERPINA3 was mainly expressed in the nucleus of cancer cells and ECM but rarely expressed in normal para-cancer tissues conducting by IHC." (PMID 33569740, 2021). "Recently, in a murine cardiovascular model, SERPINA3 was found to be upregulated and in a population of cancer survivors with CTRCD (LVEF < 50%), on average 5 years after AnC, SERPINA3 values were increased compared to an age and sex-matched control population." (PMID 40087712, 2025). "We have confirmed the correlation between IL-33 and markers like SerpinA1, SerpinA3, and EphB2 for SCC and Gli1, Gli2, FOXO3A for BCC as it highlights the complex interplay of cytokines, protease inhibitors, and receptor signaling in cancer." (PMID 39839625, 2024). "SERPINA3 is an acute-phase protein, so its expression is not a cancer-specific protein and increases in response to inflammation." (PMID 37628784, 2023). "Upregulation of 48 proteins in samples of cancer patients was reported, that included several inflammation/acute phase-related proteins: A1AG1 (ORM1), A1AT (SERPINA1), AACT (SERPINA3), CO4B, CO9, HPT, ITIH4, LBP and SAA1, which upregulation was revealed also in our study." (PMID 26376850, 2015). "At the moment, there is no consensus on the role that Serpina3 will play in the long-term treatment of HFpEF, as a beneficial treatment based on its immunomodulatory properties, or as a potential target to reduce long-term cancer mortality." (PMID 38203612, 2023). "Our findings, aligned with the existing literature, position SERPINA3 as a potential prognostic biomarker and therapeutic target in NPC and other cancers, despite it not having been previously identified in the plasma or serum of NPC." (PMID 40565234, 2025).
neurodegenerative disease (10 papers, 2007 to 2025). A disorder of the central nervous system characterized by gradual and progressive loss of neural tissue and neurologic function. "Recent studies have shown that aberrant SERPINA3 expression is closely associated with a variety of neurodegenerative diseases." (PMID 40076571, 2025). "Multiple studies have identified SERPINA3 and its subfamily SerpinA3N/SerpinA3 as common factors in neurodegenerative diseases, suggesting that they play essential roles in disease development." (PMID 39125762, 2024). "These biochemical evaluations suggested that SERPINA3/SerpinA3n upregulation can occur as a response to the augmented protease activity, which arises to counteract neurodegenerative disease–related protein aggregate accumulation." (PMID 35416570, 2022). "A SERPINA3/SerpinA3n role in neurodegenerative disease-related protein aggregation was further corroborated by in vitro SerpinA3n-dependent prion accumulation changes." (PMID 35416570, 2022). "Our results indicate SERPINA3/SerpinA3n is a potential therapeutic target for the treatment of prion and prion-like neurodegenerative diseases." (PMID 35416570, 2022). "Additionally, the SERPINA3 protein participates in the propagation of the formation of β-amyloid or prion proteins in neurodegenerative diseases, and the glycosylation of SERPINA3 can be a therapeutic tool." (PMID 39125762, 2024). "Considering both our current findings and previous studies, we speculate that differential expression of SERPINA3/SerpinA3n, and to a larger extent of many other serpins, could be shared among neurodegenerative diseases." (PMID 35416570, 2022). "Up-regulation of SERPINA3, a serine protease inhibitor enriched in neurofilament conglomerates of ALS motoneurons, can be seen in the same light and has been associated with other neurodegenerative diseases." (PMID 17244347, 2007). "An additional, not fully understood aspect of the action of the SERPINA3 protein is its participation in the propagation of the formation of pathological deposits of proteins such as β-amyloid or prion protein, described in the cases of neurodegenerative diseases." (PMID 36672665, 2023). "SERPINA3, which was increased in ALS in our study, is a glycoprotein involved in various physiological processes such as complement cascade, inflammation, and wound healing, and this protein is reported to be involved in various neurodegenerative diseases." (PMID 37238921, 2023). "Together with the relevant upregulation of SERPINA3 in sCJD and AD at early stages of NFT pathology frontal cortex, our transcriptomic analysis revealed subtle dysregulations of other SERPIN members in neurodegenerative diseases." (PMID 35416570, 2022). "SERPINA3 was also found to be significantly upregulated in the motor cortex of ALS patients and expressed four-fold more in the MSA frontal cortex compared to controls, suggesting SERPINA3 involvement in other types of neurodegenerative diseases." (PMID 35416570, 2022).
infection (7 papers, 2007 to 2025). The state of being infected such as from the introduction of a foreign agent such as serum, vaccine, antigenic substance or organism. "Plasma analysis of the patients infected with SARS-CoV2 also showed that SERPINA3 protein levels were higher in patients with increased symptoms than in patients with milder infections." (PMID 36672665, 2023). "It is, therefore, necessary to conduct further studies that will determine the function of the SERPINA3 protein in response to infection and its mechanism of action." (PMID 36672665, 2023). "The level of SERPINA3 in vivo is normally maintained at 0.3–0.6 mg/mL, and it can surge to 4-fold within 8 hours after infection, which can be used for rapid detection of acute inflammation." (PMID 36248880, 2022). "Proteins like CRP, SERPINA3,SAA1, SAA2, and immunoglobulins were previously related to SARS-CoV-2infection in the literature,−, and their abundance increasesduring the infection and returns to their normal status after 3–4weeks postinfection." (PMID 40997940, 2025). "The exacerbation observed for SERPINA3 mRNA in iCJD samples may be explained by the younger age of these patients (29 years on average) if compared to the other acquired from of CJD studied (vCJD, 35 years on average) who might display a stronger reactivity to the infection." (PMID 29142239, 2017).
neurological diseases (7 papers, 2018 to 2025). "Another study representing the first transcriptome sequencing study proposed the association of seven genes (CTSS, SERPINA1, NPTX1, PTX3, CHI3L1, SERPINA3, and MX1) as “the missing link” to explain the correlation between HHV-6A infection and neurological diseases." (PMID 35683449, 2022).
cardiovascular disease (6 papers, 2023 to 2025). "Proteomics confirmed a number of known pathways in CVT and HF development such as myocardial and mitochondrial damage, as well as an increase in SERPINA3, a protein already linked to cardiovascular disease." (PMID 38909263, 2024). "Overexpression of SERPINA3 has also been demonstrated to contribute to the pathogenesis of neurodegenerative and cardiovascular disease, suggesting potential as a possible prognostic marker." (PMID 41270070, 2025). "This is consistent with findings in humans, where increased SERPINA3 expression is found in AT from obese individuals and individuals with cardiovascular disease." (PMID 39064738, 2024). "Similarly, SerpinA3 also appears to play a protective role in cardiovascular disease." (PMID 37288300, 2023).